IRF3 (interferon regulatory factor 3)
Diseases named in the same sentence as IRF3 in open-access papers (continued):
Sharing a sentence is not in itself a finding about the gene and the disease.
infection (continued). "Interestingly, in macrophages we observed host protein degradation, especially IRF3 and STAT2, at early phases of infection with both lineage viruses, suggesting an early proteasomal activation in phagocytic cells." (PMID 31673117, 2019). "Because IRF3 plays an extremely important role in RLR pathway activation and the induction of IFN in response to infection by RNA viruses, and PPRV N protein showed a significant suppressive effect on IRF3 and the molecules upstream from it, we concentrated our subsequent investigations on IRF3." (PMID 31167907, 2019). "Hence, the JEV modulated the p-PTEN/PTEN at an early time point to enter and replicate, while at the later stages of the infection's progression, the virus suppressed the PTEN and shut down the PI3K/AKT/IRF3 axis to suppress the type-I interferon response." (PMID 31448245, 2019). "This is attained by preventing the phosphorylation and nuclear translocation of IRF3; IRF3 levels remained constant after infection unlike the 70% decrease in phosphorylated IRF3." (PMID 31574966, 2019). "Although there was an increase in the MERS-CoV titer in IRF3 knocked down/out bat cells as compared to wildtype bat (Efk3) cells, IRF3 knockout bat cells did not support MERS-CoV propagation to the same extent as MRC5 cells 48 h after infection." (PMID 30781790, 2019). "Phosphorylation of STING, and TICAM2 were inhibited, but not IRF3 phosphorylation by AKT inhibitor IV after infection." (PMID 30770800, 2019). "While STING was originally shown to activate not only IRF3 but also IRF7 and IRF3 and IRF7 have been shown to have non-redundant roles in different infection models, IRF3 is generally described in reviews as the main IRF downstream of cGAS and STING." (PMID 31877196, 2019). "During infection, these induced transcripts declined over the course of roughly 12 hours in a vhs-dependent fashion, while IRF3 phosphorylation was enhanced in the absence of vhs, reflecting the signalling events that occur when vhs is not present." (PMID 30475899, 2018). "The results also suggested that IRF3 could be activated to a greater extent after poly(I:C) stimulation and SCRV infection in host cell than after the administration of IRF2 and IRF6." (PMID 29755465, 2018). "Similarly, mOasl2 significantly enhanced the expression of RNase L and six (IRF3, IFNα, IFNβ, IFIT1, IL8, and TNFα) of 10 tested genes related to IFN signaling in A549 cells after infection by the PR8 virus." (PMID 29973937, 2018). "In contrast to COP, infection with vv811 triggered ∼7-fold increase in IFIT-1-driven GLuc activity, suggesting that the absence of immunomodulatory genes limits the ability of vv811 to block IRF-3 responses in differentiated THP-1 cells." (PMID 29491158, 2018). "In contrast, vv811 infection efficiently suppressed both p-STING and p-IRF-3." (PMID 29491158, 2018). "Interestingly, IRF3 and IRF7 were only upregulated in head kidney samples after infection with the high virulent reassortant; however, ISG15 and Mx were upregulated in both tissues analyzed." (PMID 30065724, 2018). "Notably, at 42–72 hr post-infection, pDC:Irf7+ mice displayed significantly reduced levels of DENV titer and RNA in the spleen and plasma compared to Irf3/7 DKO mice." (PMID 29914621, 2018). "While IRF3 was partially implicated in S. suis-induced IFN-β by DCs, its expression was not modulated following infection with S. suis, unlike that of IRF1 and IRF7." (PMID 28894449, 2017). "Given that Ly6Chi monocytes express type I IFN in an IRF3/IRF7-dependent manner in response to co-culture with RRV-infected cells, we next assessed whether monocytes express Irf7 and/or type I IFN during infection in vivo." (PMID 29244871, 2017). "We demonstrate that the IRF3/7 DKO mouse is a susceptible, mostly non-lethal model well suited for the study of infection kinetics, pathological progression, and antibody response." (PMID 28420392, 2017).
infection (continued). "This IRF3/7 DKO mouse strain is susceptible to ZIKV and shows similar infection kinetics as the other recent models without being 100% lethal, thus allowing for long-term studies." (PMID 28420392, 2017). "Infection of Irf3-/- mice confirmed an impairment in Mx1 and Ifit1 but not Tnf induction suggesting that IRF3 is critically involved in K. pneumoniae-elicited type I IFN production in vivo." (PMID 29112952, 2017). "Since IRF3 is a downstream signalling molecule in the STING-TBK1 axis, upregulation of miR-576-3p serves as a negative feedback loop to prevent sustained inflammatory response during and post infections." (PMID 28596706, 2017). "As IRF3 only stimulates the production of IFNs following its translocation into the nucleus, we evaluated whether virion and ISVP infection lead to similar kinetic of IRF3 nuclear translocation." (PMID 28883463, 2017). "We believe that although Csn-B may activate both IRF3 and IRF7, it might activate signaling events that lead to the phosphorylation of IRF3 more efficiently than IRF7, a process that may contribute to counter IAV in the early stages of infection." (PMID 29053748, 2017). "Finally, reconstitution of Irf3-/-;Irf7-/- mice with CCR2-DTR bone marrow rescued mice from severe infection, and this effect was reversed by depletion of CCR2+ cells, indicating that CCR2+ hematopoietic cells are capable of inducing an antiviral response." (PMID 29244871, 2017). "To further investigate downstream mechanisms of inhibition of the IFN-α/β response by ROCV prM-E proteins, we used IRF3−/− × IRF7−/− MEF cells, which lack the ability to produce IFN-α/β in response to infection, but maintain the ability to respond to exogenous IFN-α/β." (PMID 28317911, 2017). "Furthermore, reconstitution of Irf3-/-;Irf7-/- mice with CCR2-DTR bone marrow rescued mice from severe infection, and this effect was reversed by depletion of CCR2+ cells, indicating that CCR2+ hematopoietic cells are capable of inducing an antiviral response." (PMID 29244871, 2017). "In contrast Irf3 expression was not affected by either infection or the absence of Type I IFN signaling." (PMID 26918359, 2016). "Finally, the silencing of SNRNP200 completely blocks IRF3 Ser386 phosphorylation in MDM, even when IRF3 protein levels are similar to control cells, resulting in the blockage of IFN-β secretion at 3 hours post-infection." (PMID 27454487, 2016). "Since MDP pretreatment inhibited HCMV replication, and its addition after infection induced the phosphorylation of TBK, IRF3 and IFN-β expression, we hypothesized that the antiviral effects of MDP pretreatment were mediated through IFN-β." (PMID 26830977, 2016). "Epithelial expression of the antiviral genes IP-10 and IRF-3 are also higher in Muc18 KO mice, even in the absence of infection, suggesting an inhibitory effect of Muc18 on antiviral gene expression." (PMID 27701461, 2016). "PKR-null cells were infected at least as well as WT cells, as assayed by quantitation of viral RNA following infection, confirming that failure to induce IRF3 translocation was not due to a defect in infectivity of PKR-null cells." (PMID 26939124, 2016). "In ALI culture, IRF-3 was significantly increased in KO mice in the absence of infection, but unchanged when infected with HRV-1B." (PMID 27701461, 2016). "As expected, IFNβ expression was completely dependent on the presence of the transcription factor IRF3, as shown by the lack of IFNβ expression following infection of Irf3-/- cells." (PMID 26939124, 2016). "For example, infection with low particle numbers of non-replicating enveloped virus induces a subset of ISGs in an IRF3-dependent IFN-independent manner." (PMID 27809273, 2016). "MDP-pretreatment followed by infection did not further increase pIRF3, but a hyperphosphorylated form of IRF3 remained elevated in the nuclear fraction." (PMID 26830977, 2016).
infection (continued). "We therefore examined gene expression for several important interferon-related genes (IFNα2, IFNα4, IFNβ, IFNαβR, IFNγ, IFNγR, Irf3, Irf7, Mx1, Oas1, IFITM1, IFITM2), along with inflammasome-related genes IL-1β and NLRP3, and chemokines CCL5, CCL7, and CCL12 at d1 post-infection." (PMID 26110868, 2015). "Upon infection EV71 3Cpro directly binds with N terminal domain of RIG-I and impairs the interaction with the adaptor protein MAVS (also known as IPS-I /VISA/Cardif), leading to reduced activation of IRF3 and subsequent type I IFN production." (PMID 26694447, 2015). "Similarly, miR-562a was shown to be increased during virus infections (VSV), in an IRF3/IRF7-dependent manner." (PMID 26694447, 2015). "Densitometry analysis showed no statistical difference between the average of three different passages from MΦN and MΦP (p = 0.5), indicating that constitutive expression of total IRF3 is not altered by persistent RSV-infection." (PMID 26501312, 2015). "Although we found that in A549 cells, HPeV1 induced a sustainedlevel of total IRF3 at both 37°C and 39°C, phosphorylated IRF3,the activated form of IRF3, only emerged and lasted until late infection at37°C, not 39°C." (PMID 25646764, 2015). "In the case of Mycobacterium tuberculosis, mice lacking IRF3 are more resistant to infection with M. tuberculosis suggesting that IRF3 activation is detrimental to host clearance." (PMID 24391507, 2014). "We performed Western blot analysis of MVA- or WT VAC-infected cDCs, and found that MVA infection triggered IRF3 phosphorylation (which peaks at 4 h post infection), whereas WT VAC infection fails to do so." (PMID 24743339, 2014). "Electro-mobility Shift Assays (EMSA) were used to test whether IRF3(5D) from cells containing both IRF3(5D) and PLpro was able to bind to the ISG15 or OAS1b promoter, both of which are bound by IRF3 during infection." (PMID 25481026, 2014). "Western blot analysis demonstrated that MVA-induced IRF3 phosphorylation peaked at 4 and 6 h post infection in WT cDCs and was absent in StingGt/Gt cDCs." (PMID 24743339, 2014). "In contrast, infection of MEFs with knock-out of the IFN regulatory factor (IRF)-3 and -7 genes (IRF-3/7−/−; cannot effectively produce IFN-α/β but can respond to exogenous IFN) demonstrated no appreciable difference in replication efficiency between FL-IRAΔCS3 and FLSDX viruses." (PMID 24473339, 2014). "Since IRF-3 stimulates IFN-β production and IRF-7 induces both IFN-α and IFN-β production, the significance of IRFs in each infection model could possibly hint on the importance of IFN-α and/or IFN-β at different window of the liver-stage infection." (PMID 25157202, 2014). "We observed increased phosphorylation of IRF3 in HEK293-TLR3 cells compared to HEK293-NULLs likely due to the convergence of TLR3-dependent and RIG-I-dependent signaling events in response to WNV at late times post-infection." (PMID 25127040, 2014). "Furthermore, Western blot analysis demonstrated that MVAΔE3L infection induced higher level of phospho-IRF3 than MVA at both 4 and 8 h post infection." (PMID 24743339, 2014). "In the absence of drug, nuclear IRF3 was detectable in 8.8% and 35.8% of cells following infection with Ud or PR8-ΔNS1, respectively." (PMID 24478437, 2014). "At 12 h post-infection, neither phosphorylated IRF3 nor IFN-β mRNA was detected in HeLa cells that were infected with MP4, TW2231/98, or BrCr strain of EV71 (lane 3–5)." (PMID 23650567, 2013). "6A suggests that the expression level of IRF7 was higher than that of IRF3 at steady state, which would support the notion that IRF7 could act directly downstream of viral recognition to induce IFNs at the earliest stage of infection." (PMID 24278020, 2013). "This suggests that macrophages can restrict WNV-NY infection through an alternative pathway that is independent of IRF-3, IRF-5, and IRF-7, possibly through IRF-1 and/or other transcription factors." (PMID 23300459, 2013).
infection (continued). "Importantly, the JAK inhibitors also suppressed the phosphorylation and dimerization of IRF3 (panels P1 and P2), indicating that the IFNβ-stimulated JAK-STAT pathway is required to detect robust activation of IRF3 2 h post-infection/transfection." (PMID 23846693, 2013). "This experiment showed that infection of MEFs with these WR-based viruses did not induce IRF3 translocation, in contrast to the ability of MVA to activate this innate immune signalling pathway." (PMID 24098118, 2013). "Consistent with this expectation, Oasl1 KO mice turned out to be more resistant to chronic LCMV CL-13 infection as well as acute LCMV Arm infection, although LCMV is equipped with nucleoprotein (NP), a virus-derived IFN-I negative regulator that interferes with activation of IRF3." (PMID 23874199, 2013). "Unexpectedly, IRF3 deficient MTEC were not impaired in their ability to upregulate both IL-28 and IFNβ in response to infection." (PMID 24278020, 2013). "Both synthetic ssRNA and ssRNA viral genomes activated IRF-3 in a NOD2- and MAVS-dependent manner, and infection with RSV resulted in increased NOD2 expression, leading to IFN production within 2 h p.i., whereas other PRRs (e.g., RIG-I) activate the IRF-3-IFN pathway during a later infection period." (PMID 24244872, 2013). "While it appeared that Ifnβ expression was decreased in Irf3−/− and Irf7−/− mice compared to wild type on day 4 post-infection, expression of this cytokine was not fully dependent on either transcription factor." (PMID 22911267, 2012). "Wild type Y. pestis are known to survive better than pgm− strains inside activated macrophages and, in our analyses, we showed that the absence of IRF-3 had minimal effect on protection against infection by wild type bacteria." (PMID 22911267, 2012). "In the case of DENV, our group demonstrated, using a primary human cell system, that infection of human DCs with DENV did not induce IRF-3 phosphorylation, resulting in an inhibition of type I IFN production after DENV infection." (PMID 22590678, 2012). "While IRF-3 is necessary for an early stage of phagocytosis, IFNAR signaling promotes the infection and may directly contribute to neutrophil depletion during infection." (PMID 22911267, 2012). "Infection with the WT VZV leads to the up-shift of IRF3 (lane 2) whereas no up-shift is observed in cells infected with VZV ROka47S (lane 3)." (PMID 21347389, 2011). "It has been reported that NOX-derived ROS stimulate activation of the non-canonical IKK-like kinase, IKKε, and so IRF-3 activation, during infection with respiratory syncytial virus." (PMID 21949653, 2011). "In terms of source of intracellular nucleic acids, consistent with the binding activity of S100B in vitro, we found that fungal RNA not only complexes with S100B in infection but also activates epithelial cells in a TLR3–dependent manner, as indicated by IRF3 phosphorylation." (PMID 21423669, 2011). "On the contrary to HSV-1 and hCMV, our data demonstrated that VZV rapidly prevents IRF3 from homodimerization as soon as 4 hours post-infection and probably does not require de novo synthesis of viral proteins." (PMID 21347389, 2011). "By contrast, in the presence of CHX the level of IRF3 did not change during the time course of infection." (PMID 21677781, 2011). "IRF3 is not up-shifted in mock-infected mDCs (lanes 1 & 2) while infection with the WT VZV leads to the appearance of an IRF3 slower-migrating form (lanes 3 & 4)." (PMID 21347389, 2011). "Because CVB3 did not elicit a pronounced translocation of IRF3 into the nucleus during infection of HEK293 cells, we investigated the role of several PRRs in mediating CVB3 recognition–TLR3, RIG-I, and MDA5." (PMID 21436888, 2011). "In constrast, a P-fimbriated transformant triggered rapid, septic infection in the Irf3−/− but not in wt mice linking this virulence factor that recognizes glycosphingolipid surface receptors, to the IRF3-dependent host response." (PMID 20886096, 2010).
infection (continued). "Though NFkB, IRF7 and IRF3 silencing decreased ISG15 expression, only IRF7 decreased the level of the reporter gene expression by more than 50% and partially reverted the resistance to infection with Ad5GFP." (PMID 20113473, 2010). "Similarly, IRF3 and NF-κB (as assessed by luciferase assay of infected A549 cells transfected with IRF3 and NF-κB luciferase) was induced by HPIV3 during early infection (within 12 h post-infection)." (PMID 19922606, 2009). "IKKγΔ fails to support viral-induced IRF3 activation in response to ssRNA infections; consequently type I IFN production and the induction of anti-viral interferon stimulated genes (ISGs) are significantly attenuated." (PMID 19956647, 2009). "NSP1 targets IRF3, IRF5, and IRF7 for proteasome-dependent degradation early post-infection." (PMID 19180189, 2009). "However, TRAF6 is dispensable for IRF3 activation because the dimerization of IRF3, an indicator of IRF3 activation, occurred normally in Traf6−/− MEF cells following either transfection with poly I:C or infection with NDV or SeV Cm." (PMID 19479062, 2009). "Expression of NSP1 in the absence of infection directs IRF3 degradation, indicating it is the sole viral protein that mediates this effect." (PMID 19180189, 2009). "NSP1 encoded by rotavirus strains analyzed thus far directs proteasome-mediated degradation of IRF3 when expressed in the absence of infection." (PMID 19180189, 2009). "The lack of IRF-3 did not significantly influence the plasma levels of IFNαβ 4 or 8 h after infection in response to Ad." (PMID 19008951, 2008). "In the absence of IRF-3, significantly higher levels of viral RNA were observed by days 2 and 4 after infection in serum (10.6-fold, p < 0.0001; and 4.8-fold, p < 0.0001) and draining popliteal lymph nodes (2.2-fold, p = 0.03; and 5.3-fold, p = 0.02)." (PMID 17676997, 2007). "Because WNV-specific antibody responses were not blunted in IRF-3−/− mice, it is likely that the increased infection in the periphery was not due to inadequate priming of B cell responses." (PMID 17676997, 2007). "To determine whether the increased infection in IRF-3−/− macrophages was due to altered IFN levels, we analyzed the kinetics of IFN-α and IFN-β production in WNV-infected wild-type and IRF-3−/− cells." (PMID 17676997, 2007). "However, they contrast with studies of MEFs or myeloid dendritic cells whereby IRF-3 was required to fully activate IFN-α and IFN-β responses after infection with HSV, VSV, EMCV, or SFV." (PMID 17676997, 2007). "Importantly, pre-treatment with IFNλ2/3- and IRF3 KO-conditioned media failed to limit RV-UnaG infection as compared to WT-conditioned media and display similar infection levels to DMEM-F12 control media." (PMID 41525418, 2026). "However, we did not observe enrichment of MAVS or IRF3 with SGs assembled in response to Zika virus (ZIKV) or West Nile virus (WNV) infection." (PMID 38295168, 2024). "We did not detect IRF3 in either infection in the NanoString analysis." (PMID 39702382, 2024). "Transcription of genes like IRF3 and TNFα were not significantly altered upon infection." (PMID 39509467, 2024). "In our analysis, we did not detect IRF3 in both LmWT and LmCen–/– infections indicating that IRF7 alone may be sufficient to induce the type-I response following Leishmania infection." (PMID 39702382, 2024). "For this, we classified IFIT1+ infections as replicating either ‘fast’ or ‘slow/intermediate’ on the basis of split-GFP intensity time traces using the clustering algorithm described before and determined the average IRF3-BFP nuclear translocation for both groups." (PMID 37814072, 2023). "Overall, the ability of pantethine to reduce the infection-induced increases in MAVS, IRF3 and STING expression could explain the antiviral and anti-inflammatory effects of pantethine, which significantly inhibited IFNβ, TNFα and IL6 expression in infected Calu-3a cells." (PMID 36754974, 2023).